NAMPT (nicotinamide phosphoribosyltransferase)
Description:
Catalyzes the condensation of nicotinamide with 5-phosphoribosyl-1-pyrophosphate to yield nicotinamide mononucleotide, an intermediate in the biosynthesis of NAD. It is the rate limiting component in the mammalian NAD biosynthesis pathway. The secreted form behaves both as a cytokine with immunomodulating properties and an adipokine with anti-diabetic properties, it has no enzymatic activity, partly because of lack of activation by ATP, which has a low level in extracellular space and plasma. Plays a role in the modulation of circadian clock function. NAMPT-dependent oscillatory production of NAD regulates oscillation of clock target gene expression by releasing the core clock component: CLOCK-BMAL1 heterodimer from NAD-dependent SIRT1-mediated suppression (By similarity).
Synonyms: PBEF; PBEF1; 1110035O14Rik; VF; VISFATIN
Tractability: Small molecule: a drug acting on it is in phase 2 or 3 trials; a structure with a bound ligand is known; a high-quality ligand is known; it has a high-quality binding pocket; it belongs to a druggable protein family. Antibody: UniProt places it where antibodies can reach, with high confidence; its Gene Ontology location is reachable by antibodies, with medium confidence. PROTAC: ubiquitination databases record sites on it; its protein half-life has been measured; a small molecule that binds it is known.
Target class: Enzyme
Chemical probes: A-1293201, CHS-828, GNE-617 (high quality), GNE-618, PD070146, PD080678, PD080921, PD080997, PD081013, PD081227, PD081241, PD081398, PD081399, PD081458, PD081502, PD081640, PD081907, PD081935, PD082037, PD082151, and 23 more
Gene: Protein-coding gene on chromosome 7 (106,248,298 to 106,291,225, reverse strand). Ensembl gene ENSG00000105835.
Subcellular location: Nucleus; Cytoplasm; Secreted
Subcellular location (Human Protein Atlas): Nuclear speckles; Cell Junctions; Predicted to be secreted
Pathways (Reactome):
Circadian clock: BMAL1:CLOCK,NPAS2 activates circadian expression
Gene expression (Transcription): NPAS4 regulates expression of target genes
Metabolism: Nicotinate metabolism
Gene Ontology:
Molecular function: identical protein binding; nicotinamide phosphoribosyltransferase activity; protein binding; cytokine activity
Biological process: adipose tissue development; inflammatory response; insulin receptor signaling pathway; positive regulation of canonical NF-kappaB signal transduction; positive regulation of ERK1 and ERK2 cascade; positive regulation of gene expression; positive regulation of transcription by RNA polymerase II; cell-cell signaling; circadian regulation of gene expression; NAD+ biosynthetic process; nicotinate metabolic process; positive regulation of cell population proliferation; signal transduction; circadian rhythm; NAD+ biosynthetic process via the salvage pathway; NADP+ biosynthetic process
Cellular component: extracellular exosome; extracellular region; nucleus; cytoplasm; cytosol; mitochondrial matrix
Genetic constraint (gnomAD): Loss-of-function variants: 6 observed, 35.28 expected, observed/expected ratio (o/e) 0.17, 90% interval 0.092 to 0.34. The synonymous counts are far from expectation, so gnomAD's model fits this gene poorly and the ratio says little. Missense variants: 161 observed, 344.44 expected, observed/expected ratio (o/e) 0.47, 90% interval 0.41 to 0.53. Synonymous variants: 90 observed, 120.33 expected, observed/expected ratio (o/e) 0.75, 90% interval 0.63 to 0.89.
Homologues: Orthologues: chimpanzee NAMPT (99% identical), macaque NAMPT (97% identical), pig NAMPT (97% identical), mouse Nampt (96% identical), guinea pig NAMPT (93% identical), dog NAMPT (92% identical), rat Nampt (92% identical), tropical clawed frog nampt (87% identical), zebrafish nampt1 (86% identical), zebrafish nampt3.1 (79% identical), zebrafish nampt4.2 (79% identical), zebrafish nampt3.2 (77% identical), and 1 more. Paralogues in human: NAPRT (18% identical).
Diseases named in the same sentence as NAMPT in open-access papers:
NAMPT is named in the same sentence as 288 diseases in open-access papers, as found by Europe PMC text mining. Sharing a sentence is not in itself a finding about the gene and the disease. The quoted sentences say what the papers report.
Obesity (75 papers, 2010 to 2026). Accumulation of substantial excess body fat. "NAMPT is associated with the pathogenesis of obesity, type 2 diabetes and nonalcoholic fatty liver disease (NAFLD), by affecting lipid and glucose metabolism." (PMID 38347962, 2024). "NAMPT is essential for the function of adipose tissue, particularly apparent in the context of diet-induced obesity, where mice deficient in adipose Nampt fail to expand their adipose tissue to accommodate the lipid burden." (PMID 36996103, 2023). "On the other hand, NAMPT can also assist the progress of aging process, and has been implicated in many age-related disorders and diseases including obesity, diabetes, cancer, inflammatory and cardio-cerebra-vascular diseases." (PMID 23071504, 2012). "Taken together, data from the literature suggest that FTO and NAMPT represent two novel candidates potentially involved in the pathophysiology of obesity and associated metabolic disorders." (PMID 21687707, 2011). "In addition, research has pinpointed the association between NAMPT in obesity and diabetes, as well as its function in MASH, which highlights one more time the complex mechanisms within these metabolic diseases." (PMID 38768139, 2024). "The human NAMPT gene that consists of 11 exons is a highly polymorphic gene and has a wide variety of biological functions, so any defects in it may lead to IR, obesity, and inflammation that are implicated in the pathogenesis of NAFLD16." (PMID 39045924, 2024). "However, a French study including children and adults reported a rare NAMPT variant (rs10487818) associating with decreased risk of obesity." (PMID 26558825, 2015). "Since increased NAMPT levels are found in obesity, our data suggest at least one mechanism whereby obesity could confer an increased risk of periodontitis in obese individuals." (PMID 24058270, 2013). "As high serum NAMPT level was found in the patients with diabetes and obesity, the enhancement of ischemic injury in endothelial cells by NAMPT may in part explain that patients with diabetes and obesity are more susceptible to stroke attack." (PMID 23071504, 2012). "Hence, overexpression of NAMPT is usually linked to development of obesity." (PMID 30405740, 2018). "The role of NAMPT in the development of obesity is multifaceted, playing a critical role in regulating adipose tissue plasticity, food intake, and systemic glucose balance." (PMID 40775221, 2025). "Tissue-level protein analyses confirmed that NAMPT abundance increased in obesity and reduced markedly with WL, together highlighting that NAMPT is a likely driver of AT SASP." (PMID 40634602, 2025). "NAMPT, which exhibits insulin-mimetic effects, is expressed in visceral adipose tissue in both humans and mice, with its plasma levels increasing as obesity develops." (PMID 40775221, 2025). "A semiquantitative IHC analysis (H‐score) revealed that NAMPT expression was higher in overweight patients, indicating a positive correlation between NAMPT expression and obesity." (PMID 40560034, 2025). "In humans, plasma levels of NAMPT are increased during the progression of conditions such as obesity, T2D, and PCOS52,53." (PMID 38486041, 2024). "In mice, fat-specific NAMPT knockouts were resistant to high-fat-diet-induced obesity and had improved glucose tolerance." (PMID 39064738, 2024). "NAMPT is able to regulate the pathogenesis of obesity and related diseases, especially NAFLD, by affecting lipid and glucose metabolism, inflammation and apoptosis." (PMID 37559129, 2023). "In obesity, one of the main factors causing NAD+ depletion in AT is that energy or fat excess, such as HFD-feeding, inhibits NAMPT expression." (PMID 36777361, 2023). "Owing to the regulatory effects on cell metabolism, mitochondrial dysfunction, inflammatory response, and oxidative stress, NAMPT has been extensively analyzed in the treatment of cancers, obesity, and other diseases." (PMID 35903330, 2022).
Obesity (continued). "The expression of NAMPT and the level of NAD+ are reduced in WAT during obesity, and NAMPT deficiency in adipocytes markedly alters the endocrine function of WAT and the insulin sensitivity." (PMID 36010657, 2022). "It has been widely reported that NAMPT accumulation is altered in obesity and obesity‐related disorders." (PMID 34662475, 2021). "Visfatin (also known as nicotinamide phosphoribosyltransferase, or Nampt) is an adipokine produced by visceral fat tissue; its expression and plasma levels increase with the onset of obesity." (PMID 32742493, 2020). "NAMPT has been reported to be involved in various diseases and conditions, such as obesity, nonalcoholic fatty liver disease (NAFLD), type 2 diabetes mellitus (T2DM), cancer, and aging." (PMID 33488923, 2020). "In obesity, adipose tissue nicotinamide phosphoribosyltransferase (NAMPT) expression reduces, and NAD+ biosynthesis impairs." (PMID 33195370, 2020). "Recently, the newly discovered adipokine, known as nicotinamide phosphoribosyl transferase (NAMPT, visfatin), which has been associated with metabolic syndrome and obesity, has also been found to be a major cause of cancer proliferation." (PMID 31817697, 2019). "It has been demonstrated that NAMPT plays a role in the regulation of NAD/SIRT1 biological activity in obesity and insulin resistance." (PMID 31590397, 2019). "Some studies have reported plasma levels of visfatin, the product of NAMPT, increases in obese people, indicating that further research must be conducted to determine the relationship between NAMPT and obesity." (PMID 30755828, 2019). "Recently, we observed that inhibition of NAMPT significantly aggravated the high fat diet-induced obesity in mice (unpublished data)." (PMID 28449683, 2017). "For this, we evaluated NAMPT levels in children and adolescents with acute infections, chronic inflammatory diseases (active and inactive), obesity and atopic diseases in comparison to a healthy control group." (PMID 28837586, 2017). "Four common variants involved in inflammatory-adipokine triggering (IL6 rs2069845, LEPR rs1137100, NAMPT rs3801266, and AMD1 rs2796749) have recently been associated with obesity and related traits in Indian children." (PMID 26558825, 2015). "Increased serum levels of NAMPT have been found in obesity, metabolic syndrome, type 2 diabetes, atherosclerosis, and other diseases." (PMID 24288440, 2013). "High serum levels of NAMPT are found in obesity, metabolic syndrome, type 2 diabetes, atherosclerosis, and other diseases." (PMID 24058270, 2013). "Elevated level of serum NAMPT, the major form of eNAMPT, has been reported in patients with age-related diseases such as diabetes, obesity, atherosclerosis, cancers and inflammation, implying an important role of NAMPT in these disease processes." (PMID 23071504, 2012). "In this study, we evaluated the potential regulation of FTO and NAMPT as two novel candidates potentially involved in the pathophysiology of obesity and metabolic sequelae by metabolic regulators at the level of adipocytes." (PMID 21687707, 2011). "Previously, various genes including the fat mass and obesity associated (FTO) and the nicotinamide phosphoribosyltransferase (NAMPT) gene have been suggested to potentially contribute to the development of obesity and related metabolic traits." (PMID 21687707, 2011). "NAMPT, also known as pre B-cell colony enhancing factor or “visfatin”, is another novel obesity related factor and has been shown to play a role in glucose homeostasis." (PMID 21687707, 2011). "On the other hand, we investigated the clinical relationship between obesity and NAMPT expression." (PMID 40560034, 2025). "Alterations in adipokines, such as decreased levels of adiponectin and increased levels of leptin, nicotinamide phosphoribosyltransferase (NAMPT)/Visfatin, and/or resistin, trigger abnormalities in MSC functions that promote obesity-associated illnesses and alter the response to MSC therapy." (PMID 40893809, 2025).
Obesity (continued). "However, in obesity, a decrease in NAD+/NADH ratio is associated with an increase in NAMPT levels, paradoxically." (PMID 39901373, 2025). "Nicotinamide ribosyl transferase (NAMPT) is an enzyme that is highly expressed in the liver and is involved in the progression of tumors in obesogenic environments, having been shown to have increased concentrations in the context of obesity." (PMID 40722609, 2025). "While NAMPT-deficient mice do not develop obesity during aging, they exhibit severe insulin resistance in skeletal muscle, cardiac tissue, and WAT, accompanied by hyperinsulinemia and hypoadiponectinemia." (PMID 40775221, 2025). "Additionally, obesity triggers the vicious cycle by decreasing the enzyme nicotinamide phosphoribosyl transferase (NAMPT), which catalyzes the rate-determining step for NAD+ synthesis and NAD+ levels in human tissues." (PMID 36769283, 2023). "None of the rare NAMPT variants discovered have previously been described as being associated with obesity." (PMID 37888112, 2023). "Interdicting metabolic disease at the level of NAD+ biosynthesis and/or hepatocyte glucose transport are proximal targets that may leverage the broader effects of hepatocyte NAMPT activation against aging, obesity, and other fasting-responsive diseases." (PMID 35228549, 2022). "Obesity also reduces NAMPT by inducing the expression of miR34a." (PMID 33384409, 2021). "NAMPT modulates processes involved in the pathogenesis of obesity and related disorders by influencing the oxidative stress response, is often overexpressed in tumor tissues, and potentially contributes to the ability of cancer cells to resist oxidative stress." (PMID 33488923, 2020). "An improvement of NAMPT protein and NAD levels by the bioflavonoid troxerutin or leucine was shown to protect mice with diet-induced obesity against steatosis, inflammation and glucose intolerance indicating an important role of NAMPT in the development of NAFLD." (PMID 28974242, 2017). "Recently, we observed that FK866 significantly aggravated the high fat diet-induced obesity in mice, in which the NAMPT inhibition-induced obesity might be involved in suppression of Sirt1-SREBP1-FASN signaling pathway in adipose cells (unpublished data)." (PMID 28449683, 2017). "Nicotinamide phosphoribosyl transferase (NAMPT) is an inflammatory adipocytokine shown to interact in immune modulation in chronic inflammatory diseases, acute respiratory distress syndrome, sepsis, cancer and obesity in adulthood." (PMID 28837586, 2017). "Moreover, human monocyte expression of NAMPT is more closely related to parameters of glycemia, whereas resistin correlates more strongly with obesity." (PMID 24968098, 2014). "Enhanced levels of NAMPT, as found in obesity and periodontal inflammation, may compromise the regenerative capacity of PDL cells and, thereby, periodontal healing in the presence of EMD." (PMID 24288440, 2013). "The findings of this study suggest that increased levels of NAMPT, as found in obesity and periodontal inflammation, may compromise the regenerative capacity of PDL cells and, thereby, periodontal healing in the presence of EMD." (PMID 24288440, 2013). "Enhanced levels of NAMPT, as found in obesity and periodontal inflammation, may compromise the regenerative capacity of PDL cells and, thereby, regenerative periodontal healing in the presence of EMD." (PMID 24288440, 2013). "Increased NAMPT levels, as found in obesity, may therefore represent a mechanism whereby obesity could confer an increased risk of periodontitis." (PMID 24058270, 2013). "Therefore, estradiol could mitigate the effects of obesity on UAM damage by enhancing SIRT1‐mediated NAMPT deacetylation, providing insights into sex differences in obesity‐associated OSA." (PMID 39901373, 2025). "Thus, NAMPT could be an effective therapeutic target for preventing and treating metabolic disorders, including obesity and type 2 diabetes mellitus, inflammation, and cancer." (PMID 38956704, 2024).